MMP2 (matrix metallopeptidase 2)
Diseases named in the same sentence as MMP2 in open-access papers (continued):
Sharing a sentence is not in itself a finding about the gene and the disease.
fibrosarcoma (continued). "Analysis revealed a positive correlation between u-PA and MMP-2 expressions of NM-treated adult sarcoma cell lines, the fibrosarcoma HT-1080, chondrosarcoma SW1353, and liposarcoma SW-872, as shown in Table II." (PMID 23661254, 2013). "Lipopolysaccharide (LPS) stimulated expression of MMP-2 in fibrosarcoma and chondrosarcoma while inhibited it in liposarcoma." (PMID 24085323, 2013). "Sensitivity to doxycycline was nearly equivalent in MMP-2 expression, but fibrosarcoma expression of MMP-9 was significantly more sensitive to doxycycline than were the other cell lines." (PMID 24085323, 2013). "IL-1β had a slight inhibitory effect on fibrosarcoma, liposarcoma and synovial sarcoma MMP-2 and MMP-9 except for MMP-9 in synovial sarcoma which showed slight stimulation." (PMID 24085323, 2013). "Further biological tests by gelatin zymographic analysis revealed that 3−5 significantly up-regulated the expressions and activation of MMP-2 and -9 in human fibrosarcoma cell line HT1080." (PMID 22354186, 2012). "Park and his colleagues indicated that propylene glycol monomethyl acetic ether (PMA) treatment resulted in IκBα phosphorylation in fibrosarcoma cells, which enhances MMP-2 production through the activation of NF-κB transcription factors." (PMID 19816602, 2009). "In 2004, Jay’s group at Tufts University first reported the identification of a secreted protein from the conditioned medium of a fibrosarcoma cell line, HT-1080, and showed that the secreted protein promoted tumour cell invasion in vitro by activating the matrix metalloproteinase 2 (MMP2)." (PMID 35883467, 2022). "A significant negative correlation was found between NM modulation of Matrigel invasion inhibition and MMP-2 secretion with fibrosarcoma HT-1080 (r=−0.911), chondrosarcoma SW-1353 (r=−0.942), liposarcoma SW-872 (r=−0.957) and synovial sarcoma SW-982 (r=−0.878)." (PMID 23661254, 2013). "MMP-2 and-9 expression of chondrosarcoma and fibrosarcoma cells treated with IL-1β 10 ng/ml were downregulated by NM treatment in a dose-dependent manner with MMP-2 block at 1000 μg/ml NM and MMP-9 total block at 100 μg/ml NM in fibrosarcoma and at 1000 μg/ml in chondrosarcoma." (PMID 24085323, 2013). "Significant negative correlations were found between NM modulation of Matrigel invasion inhibition and MMP-2 secretion with fibrosarcoma HT-1080 (r= −0.911), chondrosarcoma SW-1353 (r= −0.942), liposarcoma SW-872 (r= −0.957) and synovial sarcoma SW-982 (r= −0.878)." (PMID 24085323, 2013). "MMP-2 and-9 expression of chondrosarcoma and fibrosarcoma cells treated with TNF-α 10 ng/ml were downregulated by NM treatment in a dose-dependent manner with MMP-2 block at 1000 μg/ml NM and MMP-9 total block at 500 μg/ml NM in fibrosarcoma and 99% block at 1000 μg/ml in chondrosarcoma." (PMID 24085323, 2013). "Ent-abietane-type diterpenoids such as compounds 3–5 significantly up-regulated the expressions and activation of MMP-2 and -9 in human fibrosarcoma cell line HT1080, and could potentially be leads for the development of novel wound-healing drugs." (PMID 22354186, 2012). "Inhibits MMP-2 and MMP-9, which play an important role in cancer progression, in HT1080 fibrosarcoma cells." (PMID 35208993, 2022). "In particular, transient and dose-dependent upregulation of extracellular MMP-2 and MMP-9 have been observed in irradiated cell lines derived from pancreatic cancer, glioma, lung cancer, melanoma, fibrosarcoma, and hepatocarcinoma." (PMID 30105016, 2018). "In human fibrosarcoma cells (HT-1080), TPL can modulate the expression and activity of both MMP-2 and MMP-9, and it can reduce invasiveness by directly lowering MMP-9 gene expression and activity." (PMID 27073100, 2017). "It is also interesting to note that PBK/TOPK inhibitor was likewise able to inhibit gelatinase activity in a fibrosarcoma cell line, HT1080, which expresses very high levels of MMP-2 and -9." (PMID 25909225, 2015).
fibrosarcoma (continued). "Mice with fibrosarcoma treated with CXCL10 combined with hypothermia presented reduced tumor burden and MVD, whereas the MMP2-inhibitor TIMP2, have been recently described as important prognostic factors in acute lymphoblastic leukemia." (PMID 26099922, 2015). "It has been experimentally demonstrated that the standardized aRVS extract has antiangiogenic activities by inhibiting VEGF and an inhibitory effect on matrix metalloproteinase-2 (MMP-2) and MMP-9 activities in a human fibrosarcoma cell line." (PMID 23710214, 2013). "Functionally, CD97 has been shown to promote cell migration and invasion, as well as increase expression and secretion of matrix metalloproteinase-2 (MMP2) and MMP9 in the fibrosarcoma cell line HT1080." (PMID 23658650, 2013). "Table III shows the quantitative densitometry results from the effects of natural inhibitors EGCG, the NM and retinoic acid on MMP-2 and MMP-9 expression in chondrosarcoma, fibrosarcoma, liposarcoma and synovial sarcoma cell lines." (PMID 24085323, 2013). "In this study, we investigated the effects of selected cytokines, inducers and inhibitors affecting cancer cell metabolism on the regulation of MMP-2 and MMP-9 activities in chondrosarcoma, fibrosarcoma, liposarcoma and synovial sarcoma cell lines." (PMID 24085323, 2013). "We examined the effect of cytokines, mitogens, inducers and inhibitors on MMP-2 and MMP-9 secretion in chondrosarcoma (SW-1353), fibrosarcoma (HT-1080), liposarcoma (SW-872) and synovial sarcoma (SW-982) cell lines." (PMID 24085323, 2013). "We thank Dr Carlos López-Otín and Dr Xose S Puente (University of Oviedo, Spain) for kindly providing pcDNA3-human MMP-2, pCEP-Puro-MMP-2 and pCEP-Puro-mutMMP-2 plasmids, and HT-1080 fibrosarcoma cells conditioned medium." (PMID 18349846, 2008). "Moreover, in TPA-induced HT-1080 fibrosarcoma cells, XN suppressed both the activation and expression of MMP-9 and MMP-2, reduced the MT1MMP mRNA level, and induced a substantial TIMP-1 and TIMP-2 depletion." (PMID 34204745, 2021). "The anthocyanins inhibited migration and invasion of MDA-MB-453 cells (HER2+), suppressed activation of rapidly accelerated fibrosarcoma, mitogen-activated protein kinase (MEK), and c-Jun N-terminal kinase (JNK), as well as downregulated secretion of matrix metalloproteinase 2 (MMP2) and MMP9." (PMID 28970777, 2017). "In this in vitro study, the NM significantly inhibited secretion of u-PA and MMP-2 and/or -9 and increased secretion of TIMP-2 in fibrosarcoma, chondrosarcoma, liposarcoma and uterine leiomyosarcoma cells, suggesting its potential in modulating cancer invasion and metastasis." (PMID 23661254, 2013). "Type IV collagen has been shown to mediate pro-MMP-2 activation in HT1080 cells, a human fibrosarcoma cell line, without inducing either a transcriptional modulation of MMP-2 or MT1-MMP expression nor any alteration of MT1-MMP protein synthesis or processing." (PMID 15272933, 2004). "We verified the mass spectrometry result with co-immunoprecipitation of Hsp90α and tPA in conditioned media from HT-1080 fibrosarcoma cells, the cell line for which we originally discovered the interaction of extracellular hsp90α and MMP-2, and MDA-MB231 cells (data not shown)." (PMID 20553606, 2010). "Several studies have documented that the suppression of IκBα could induce NF-κB nuclear translocation and consequently promote the increase of MMP-2 in several types of human cells including Ewing sarcoma EW7 cells, human skin cells, murine melanoma cells, and HT1080 (fibrosarcoma) cells." (PMID 19816602, 2009). "Moreover, treatment of Wehi-164 fibrosarcoma cells with aqueous extract of spearmint led to significant reduction in MMP-2/MMP-9 activity in a dose-dependent manner, as there was no detectable activity of MMP-2/MMP-9 in Wehi-164 cells treated with 10 mg/mL of the extract after 24, 48, and 72 h." (PMID 33672486, 2021).
fibrosarcoma (continued). "With a highly potent invasive potential, the fibrosarcoma HT1080 cells exhibit aberrant secretion of MMP-2 and MMP-14, which acts as the receptor of TIMP2; accordingly, this may be the mechanistic basis for selective intense binding of the TIMP2-based protein LT to fibrosarcomas." (PMID 29250984, 2018). "The inhibition of MMP-2 production by DTD does not seem to be endothelial-spe-cific, since a similar effect was observed in HT-1080 fibrosarcoma cells." (PMID 18782185, 2008). "NAMI-A can directly inhibit the enzymatic activity of MMP-2 and MMP-9, as shown by the zymography performed with conditioned medium of fibrosarcoma (HT-1080) and neuroblastoma (SK-N-BE) tumour cells (data not shown)." (PMID 11953835, 2002). "As expected, a significant positive correlation was found between the secretion of u-PA and MMP-2 and a significant negative correlation between u-PA and TIMP-2 and between MMP-2 and TIMP-2 secretion by NM treatment of fibrosarcoma, chondrosarcoma and liposarcoma cells." (PMID 23661254, 2013).
non-small cell lung carcinoma (58 papers, 2001 to 2025). A group of at least three distinct histological types of lung cancer, including non-small cell squamous cell carcinoma, adenocarcinoma, and large cell carcinoma. "MMP-2 and the degradation of TN-C are associated with tumor recurrence in early-stage non-small cell lung cancer." (PMID 26770971, 2015). "The MMP2 -735 T/T genotype was statistically significantly associated with a decreased survival in non-small cell lung cancer (NSCLC) patients, identified as an independent prognosis factor of survival (hazard ratio (HR) = 1.79; 95% CI: 1.00-3.20)." (PMID 22455335, 2012). "For instance, CTS can suppress the expression of matrix metalloproteinases 2/9 (MMP2/9) and inhibit the migration and proliferation of non-small cell lung cancer through the PI3K/Akt/mTOR signaling pathway." (PMID 41446797, 2025). "Activation of the Rac1-P38-ATF2 signaling pathway in non-small cell lung cancer cells has been documented to upregulate the expressions of Cyclin A2, Cyclin D1, and MMP2 proteins, thus promoting tumor growth." (PMID 39633985, 2024). "These include SPARC, an extracellular glycoprotein that promotes metastasis in non-small-cell lung cancer, and MMP2 (matrix metalloproteinase 2), which is an activator of TGFβ and promotes cancer cell invasion by degrading type IV collagen." (PMID 39482615, 2024). "Among the MMP family, MMP-2 promotes tumor growth, tissue invasion, angiogenesis, and metastasis, and its overexpression might be associated with tumor progression and a poor prognosis for ovarian epithelial carcinoma, oral cavity cancers, and non-small cell lung cancer patients." (PMID 35701829, 2022). "A previous study showed that BBR inhibits cell proliferation and promotes apoptosis of non-small-cell lung cancer via the suppression of the MMP-2 signaling pathways." (PMID 33802664, 2021). "Loss of E-cad stimulates EGFR-MEK/ERK signaling, which promotes invasion via the ZEB1/MMP2 axis in non-small cell lung cancer." (PMID 31952541, 2020). "“Linear programmed necrosis” in non-small cell lung cancer induces tumor cells to die linearly and provides space for VM formation; second, it promotes the expression of MMP2, Twist1 and Slug, promoting extracellular matrix remodeling and EMT by DKK1, which in turn promotes VM formation." (PMID 37217473, 2023). "Tumor growth factor (TGF)-β1-mediated exosomes derived from non-small cell lung cancer destroyed tight junctions and the integrity of endothelial monolayers and the blood-brain barrier in mice via lnc-MMP2-2, promoting brain metastasis of non-small cell lung cancer." (PMID 35813192, 2022). "ECG also could inhibit the invasion of non-small cell lung cancer (NSCLC) cells by inhibiting the expression of matrix metalloproteinase-2 (MMP-2) and urokinase-type plasminogen activator (uPA)." (PMID 36505462, 2022). "Interestingly, the expression of LOX was found significantly correlated with MMP2/MMP9 expression in metastatic non-small-cell lung carcinoma (NSCLC)." (PMID 32793478, 2020). "Likewise, the inhibition of migration and invasion of non-small cell lung cancer (H838 and H520) cells by phloretin treatment was mediated through suppression of MMP-2 and MMP-9 at both gene and protein levels." (PMID 30642127, 2019). "In addition, MMP-2 was found to be better prognostic marker in non-small cell lung carcinoma patients than MMP-936." (PMID 27811960, 2016).
non-small cell lung carcinoma (continued). "In Non-small cell lung cancer (NSCLC) signaling activates PI3K/Akt promoting VEGF-C/D, MMP-2/9, aTIMP-1/2, and NF-κB, supporting tumor growth, survival and invasion." (PMID 41050670, 2025). "In non-small cell lung cancer (NSCLC), CCL2 reduces E-cadherin levels and upregulates vimentin, MMP-2 and MMP-9 protein levels through PI3K/Akt/mTOR to activate EMT." (PMID 41341593, 2025). "Angelicin inhibits A549 non-small-cell lung carcinoma (NSCLC) growth and metastasis by reducing MMP-2,9; increasing E-cadherin expression levels and JNK, and ERK activation." (PMID 32781533, 2020). "Indeed, KDELR2 overexpression promotes the metastatic phenotype in non-small cell lung cancer (NSCLC) by increasing MMP1, MMP2 and MMP9 secretion and thus cell invasive ability." (PMID 35399533, 2022). "Moreover, MMP-2 and MMP-9 also contribute to epirubicin resistance in non-small-cell lung cancer and breast cancer." (PMID 34654351, 2021). "We have previously reported that TGF-β1-mediated non-small cell lung cancer (NSCLC) cell exosomes might increase the permeability of lung vascular ECs and downregulate its tight junctions via lnc-MMP2-2." (PMID 34285192, 2021). "Similarly, in non-small cell lung cancer, two studies have demonstrated that SNHG15 knockdown suppresses tumorigenesis by inhibiting the expression of EMT, MMP2, and MMP9 and regulating the miR-486/CDK14 axis." (PMID 33243205, 2020). "Similarly, a study conducted in the A549 human non-small-cell lung carcinoma cell line, FAK-Src, ERK1/2 and β-catenin regulate the expression of MMP-2 and MMP-9." (PMID 31554180, 2019). "Exosomal miR-3157-3p from non-small cell lung carcinoma (NSCLC) cells promotes pre-metastatic niche formation, angiogenesis, and increased vascular permeability by targeting tissue inhibitor of metalloproteinase (TIMP)/KLF2, which regulates the expression of VEGF, MMP2, MMP9, and occludin in ECs." (PMID 40002766, 2025). "JWH-105 inhibited EMT in non-small cell lung cancer cells (NSCLC) by suppressing ERK and STAT-3 activation and EGFR signaling; in addition, JWH-105 reduced invasiveness of A549 cells when co-cultured with M2 macrophages, by downregulating the expression of FAK, VCAM1, and MMP-2." (PMID 33922795, 2021). "Moreover, EFEMP1 expression is also found to be regulated by promoter methylation in non-small-cell lung cancer (NSCLC) cells, and EFEMP1 could negatively modulate MMP-7 and MMP-2." (PMID 33381589, 2020). "Similarly, another study has demonstrated that miR-29b in non-small cell lung cancer models could suppress cells proliferation, migration and invasion by targeting the 3’-UTR of MMP2 and PTEN mRNA." (PMID 29361687, 2018). "After immunohistochemical staining of clinical non-small cell lung cancer (NSCLC) specimens to determine the expression levels of the components of this network, a three-step approach was used to integrate the prognostic values of uPA, uPAR, PAI-1, PAI-2, MMP-2, and MMP-9." (PMID 26230665, 2015).
Arthritis (56 papers, 2005 to 2026). Inflammation of a joint. "MMP-2 is associated with pathological tissue destruction in chronic diseases, such as cancer and arthritis." (PMID 30363968, 2018). "Mutations in the MMP-2 gene lead to a number of disease processes, such as arthritis and metastasis, tumor growth vascular aneurysmal disease development, Winchester syndrome, and nodulosis-arthropathy-osteolysis (NAO) syndrome." (PMID 29122006, 2017). "The Mmp2-deficient mice showed significantly exacerbated arthritis compared with wildtype mice, suggesting a suppressive role of Mmp-2 in this model." (PMID 21190566, 2010). "By contrast, in antibody-induced arthritis, arthritis was found to be more severe in MMP-2 gene-deficient compared with wild-type mice." (PMID 16872482, 2006). "To elucidate the role of MIF in MMP-2 production, we produced zymosan-induced arthritis (ZIA) in MIF gene-deficient and wild-type mice." (PMID 16872482, 2006). "AP1 has been linked to other inflammatory diseases, such as arthritis, and has been shown to regulate MMP-2, which could degrade extracellular matrix in IA." (PMID 33156839, 2020). "MMP2 and MMP9 are enzymes that facilitate the restructuring of the ECM and have been implicated in the pathogenesis of arthritis." (PMID 39028255, 2024). "As a result of blood inflammatory cytokine analysis using an ELISA kit, it was confirmed that the expression levels of TNF-α, IL-6, PGE2, MMP-2, and NO were significantly increased in the serum of mice with arthritis induced by MIA." (PMID 37623223, 2023). "Inline, MMP-2 expression in normal adult cartilage is weak due to very low collagen turnover, and it is upregulated in arthritis." (PMID 32111016, 2020). "An example of such a disease is arthritis, where MMP-2 is a disease suppressor whereas MMP-9 contributes to pathology." (PMID 28369077, 2017). "Our in vivo arthritis model demonstrated a clear therapeutic benefit derived from systemic administration of a MMP-2-cleavable peptide complex to reduce the inflammatory cascades associated with destructive arthritis." (PMID 27741237, 2016). "Given that MIF regulates the expression of MMPs during pathological inflammatory responses such as arthritis, we investigated the possible involvement of MMP-2 and MMP-9 in T. gondii-induced MIF-mediated ileitis." (PMID 21977228, 2011). "As expected, a number of altered proteins identified have links to arthritis, including Mmp-2, TGFβ, Fstl1, and Hp." (PMID 21589862, 2011). "APC reduced the MMP-9 levels in fibroblasts and monocytes of arthritis patients, but up-regulated and activated MMP-2." (PMID 20356362, 2010). "To evaluate the in-vivo role of MIF in MMP-2 production, we induced acute arthritis by intra-articular injection of zymosan in MIF gene-deficient and wild-type mice." (PMID 16872482, 2006). "The beneficial role of MMP2 in the development of arthritis has been recently suggested in the animal model." (PMID 16207317, 2005). "Surprisingly, they found that MMP-2 knockout mice display a more severe arthritis than wild-type mice." (PMID 15642138, 2005). "It was found that HC could reduce foot swelling in CIA rats, lower the arthritis index, and decrease the secretion of MMP-2, MMP-3, TNF-α, and IL-6." (PMID 41508102, 2026). "MMP14 is one of the MMPs involved in arthritis and activates MMP-2 and 1346." (PMID 40087276, 2025). "MMP2 is involved in various physiological and pathological processes such as tissue remodeling, cancer metastasis, cardiovascular diseases, and arthritis." (PMID 39518808, 2024). "In addition, SIN improved arthritis in rats by inhibiting pro-inflammatory cytokines IL-1β and IL-6, inhibiting MMP-2/-9, and increasing TIMP-1/-3." (PMID 38276618, 2024).